CDC42 (cell division cycle 42)
Diseases named in the same sentence as CDC42 in open-access papers (continued):
Sharing a sentence is not in itself a finding about the gene and the disease.
tumor (continued). "Typically, migration and invasion of tumor cells is promoted by the loss of interaction of adherens junctions with the cytoskeleton and subsequent changes in the activities of Rho family small GTPases such as Rac1 and Cdc42." (PMID 23300597, 2012). "Cdc42-deficiency resulted in a significant reduction in xenograft tumor growth." (PMID 22719838, 2012). "Because PI3K/Akt and MAPK pathways are often aberrantly activated in tumor cells, and they are reported to be associated with Cdc42 and huntingtin, thus we performed qRT-PCR to determine the mRNA expression of Akt and MAPK14 (encoding p38 MAPK) in Trip10-overexpressed CP70 and IMR-32 cells." (PMID 21299869, 2011). "Therefore, targeting Rac and Cdc42 in tumor-associated macrophages (TAMs) could inhibit a cascade of events that promote a tumorigenic microenvironment." (PMID 37397366, 2023). "On the basis of the remarkable role of CDC42 in the processes underlying tumor formation, newly recognized regulatory mechanisms for CDC42 and CDC42-related signaling pathways, such as lncRNAs, may inhibit the process of neoplastic transformation by impeding the abnormal overexpression of CDC42." (PMID 34771549, 2021). "In addition, we found that PAD2 depletion suppresses the expression of the cytoskeletal regulatory proteins RhoA, Rac1, and Cdc42 and also promotes a mesenchymal to epithelial-like transition in tumor cells with an associated increase in the cell adhesion marker, E-cadherin." (PMID 28549415, 2017). "Interestingly, PIK3CA mutations are associated with K-Ras mutations in advanced tumours, which may result in constitutively active Cdc42 in these cells." (PMID 27919038, 2014). "It is possible that Cdc42-null cells might more easily dissociate from the tumor or be more susceptible to clearance by the immune system; these results indicate that loss of Cdc42 in oncogenic Ras transformed cells causes a growth disadvantage in vivo as well as in vitro." (PMID 22719838, 2012). "Thus it suggests that partial inhibition of CDC42 could be enough to cause a lethal condition in those tumor cells where an amorphic mutation for PPP6C exists." (PMID 20015360, 2009). "In a previous study, it was reported that inhibiting CDC42 activity in regulatory T cells (Tregs) can enhance anti‐tumor immunity." (PMID 39791593, 2025). "In HNC, CDC42 enhances tumor cell migration and invasion by promoting cytoskeletal remodeling and EMT, and elevated levels are associated with tumor aggressiveness." (PMID 40606440, 2025). "In a 2021 study published in Molecular Therapy Nucleic Acids, researchers demonstrated that miR-497 acts as a tumor suppressor in GC by directly targeting CDC42." (PMID 41244835, 2025). "Tumor cells produced microvesicles packaged glutaminase 1 (GLS1) via cell division cycle 42 (CDC42) that promoted M2 TAMs polarization and contributed to trastuzumab resistance." (PMID 40599798, 2025). "The ncRNA-MP pTINCR is able to facilitate sumoylation to modulate Cdc42 activity to influence epithelial differentiation and tumor suppression." (PMID 40361481, 2025). "One of the oncogenic effectors associated with Cdc42 is PI3K, and the Akt signaling pathway activated by the EGFR-Cdc42 is significantly linked to tumor recurrence and resistance." (PMID 40634295, 2025). "Animal experiments also revealed that the combination of the CDC42 inhibitor (ML141) with anti‐PD‐1 blockade can additively reduce tumor growth." (PMID 39791593, 2025). "Given CDC42's established role in tumor cell migration, we performed in silico docking using AlphaFold 3, predicting direct COA4‐CDC42 binding." (PMID 40936169, 2025). "Our study also aims to demonstrate how CDC42 inhibitors can potentially enhance the anti‐tumor effects of ICI therapy, particularly in cases where tumors exhibit resistance to ICI therapy." (PMID 39791593, 2025).
tumor (continued). "Cdc42 is crucial in tumor generation, invasion, and metastasis because of its role in essential physiological processes, including cytoskeleton and microtubule regulation, transcription, cell cycle progression, and apoptosis." (PMID 40284221, 2025). "In recent times, the role of Rho GTPase Activating Protein17 (ARHGAP17) as a tumor suppressor and negative regulator for Cdc42 and Rac1 has been the subject of investigation by researchers." (PMID 40969409, 2025). "Functionally, yeast COA4 is capable of regulating mitochondrial COX activity and OXPHOS in human cells and even interacts with human CDC42 to facilitate tumor cell metastasis, underscoring its evolutionary conservation." (PMID 40936169, 2025). "Mechanistically, COA4 enhances tumor cell migration through dual pathways: within mitochondria, it boosts oxidative phosphorylation; in the cytoplasm, it binds and activates CDC42 to stimulate pseudopodia formation." (PMID 40936169, 2025). "CDC42 downstream signals play a role in promoting various aspects of tumor development, including tumorigenesis, progression, invasion, and metastasis." (PMID 39791593, 2025). "CDC42 is a type of ras homologous (rho) GTPase that stimulates tumor genesis, progression, invasion and metastatic." (PMID 39791593, 2025). "We looked at the CNA genetic landscape of the tumours of the examined patients and found that deletion of the CDC42 gene locus (1p36." (PMID 38429285, 2024). "To further prove that CDC42 reduction in iNKT cells led to impaired motility and anti-tumor function, we overexpressed CDC42 in iNKT cells." (PMID 38332012, 2024). "Cdc42 and Rac1 are important therapeutic targets in ovarian cancer since these two proteins play a critical role in tumor cell migration, adhesion, and invasion." (PMID 39769207, 2024). "The tumor driver CTNND1 is the key component involved in cell–cell adhesion and Rac1, Cdc42, and Ras homolog gene family member A (RhoA) activation and has been reported to repress the migration and invasion of tumor cells." (PMID 39338204, 2024). "When mouse CD8 T cells were co-cultured with MC38 tumor cells in vitro, they reduced CDC42 expression, and antibodies against VCAM1 or CD49d partially restored their CDC42 expression." (PMID 38332012, 2024). "Previous studies showed that the R‐enantiomer of ketorolac selectively inhibits Rac1 and Cdc42 and reduces tumour growth, invasion and metastasis." (PMID 38302863, 2024). "Silencing Cdc42 with siRNA has been shown in vitro to reprogram pericytes, changing their phenotype from a tumor-promoting, angiogenic state to a tumor-suppressive one, resembling pro-inflammatory M1 macrophages." (PMID 39796646, 2024). "We showed that MC38 tumor cells downregulated CDC42 expression in iNKT cells in vitro, and that was restored by antibodies against either VCAM1 or CD49d." (PMID 38332012, 2024). "In conclusion, p120 can bind to Rho to exert the effect of RhoGDI to inhibit Rho or activate Rac and cdc42 to promote tumor invasion and migration." (PMID 39498333, 2024). "In the delCDC42 group of patients, the frequency of tumours with 2 or more amplifications of the stemness gene (a very poor prognostic factor) was 78% (28/36), versus 58% (63/108) in the normal or amplified CDC42 group (p = 0.045)." (PMID 38429285, 2024). "The RNA-seq and protein expression of CDC42 in tumor and comparison tissues were analyzed based on the online tools; CDC42 was remarkably boosted in tumor tissues compared to normal controls." (PMID 37476838, 2023). "This study sheds light on the effects of Rac and Cdc42 inhibitors on immune response modulation within the tumor microenvironment." (PMID 37397366, 2023). "This anti-tumor activity was further corroborated by down regulation of Rac-1/Cdc42/HIF-1α/DDX3/β-catenin signalling." (PMID 37024613, 2023).
tumor (continued). "We posit that Rac and Cdc42 orchestrate the cross-talk signaling and invasion of immune cells that migrate into the tumor and the metastatic cancer cells that leave the primary tumor." (PMID 37397366, 2023). "And CDC42/MAPK pathway was proved to play a key role in the regulation of tumor growth, metastasis and drug resistance." (PMID 36849460, 2023). "In particular, it is known that GRF2 suppresses CDC42-mediated cell movements and cytoskeletal dynamics in tumor cells In this regard, it has been shown that GRF2 can bind to 14-3-3 proteins, while 14-3-3 proteins can bind and increase CDC42 activity." (PMID 37947653, 2023). "We show here that uPAR reinforces the MEK/ERK signaling pathway in tumor cells with a KRAS mutation with the suppression of FAK and CDC42 signaling." (PMID 36900379, 2023). "pTINCR increases CDC42 SUMOylation and promotes its activation, leading to epithelial differentiation and tumor suppression, which acts as a tumor suppressor in epithelial cancers." (PMID 36911524, 2023). "Cell growth assays and Western blot analysis revealed that CDC42/PAK/MLC2-regulated cell stiffness plays an important role in the SEC2/ST-4-induced CTL killing of tumor cells." (PMID 37511553, 2023). "DSCR8, another lncRNA, promotes tumor cell progression in GC patients by acting as a miR-137 sponge and positively regulating Cdc42 expression." (PMID 37670949, 2023). "The activated CDC42 can regulate the expression of the family of p21-activated protein kinases (PAKs), which are generally highly expressed in tumor cells." (PMID 36812247, 2023). "This indicates another important role of the Cdc42 signaling pathway as it can be used to prevent PCs from transforming into macrophage-like cells and, subsequently, favoring tumor survival over its clearance." (PMID 37174724, 2023). "TIMER2.0 was applied to study the mRNA expression levels of CDC42 for the entire 33 tumors in the TCGA database to explore the difference in CDC42 expression between tumors and adjacent tumor-free tissues." (PMID 37476838, 2023). "Activation of CDC42 facilitates tumor cell survivability and microadenoma formation, so CDC42 is considered to be crucial for tumorigenesis." (PMID 36812247, 2023). "A polarity-regulating GTPase in cells, known as cell division cycle 42 (CdC42), has been proven to have its overactivation tightly connected to high tumor malignancy." (PMID 37476838, 2023). "Cdc42-dependent contacts lead to recruiting of preexisting vessels and, therefore, to tumor progression in glioblastoma." (PMID 37686288, 2023). "Rho GTPases, a kind of regulator for intracellular actin dynamics, mainly consisting of RhoA, Rock1/2, Cdc42, and Rac1, can dramatically interfere with the motility of tumor cells." (PMID 36969843, 2023). "Despite the several studies that have revealed that Palladin promotes tumor cell invasion by regulating the activity of Cdc42,16 its specific mechanisms for regulating stem‐cell properties have never been reported previously." (PMID 36047666, 2023). "The reorganization of the cytoskeleton during tumor cell migration and invasion is typically dependent on Cdc42-mediated stimulation." (PMID 37670949, 2023). "Activated Rac/Cdc42 was detected in tumor cells in all stages and was especially higher in stage IV, whereas no activity was found in the corresponding normal mucosa." (PMID 35110666, 2022). "Rho family proteins including RhoA, CDC42, and Rac are key regulators of the actin cytoskeleton and play an important role in tumor metastasis." (PMID 36499486, 2022). "Consistent with the role of RAC1, PAK1, and CDC42 in regulating inducible macropinocytosis, analysis of the TCGA dataset revealed higher expression of RAC1, PAK1, and CDC42 in HCC tissues than in non-tumor lesions." (PMID 35287706, 2022). "Several publications describe the importance of CDC42 for tissue differentiation, supporting its tumor suppressor role in certain contexts." (PMID 36369429, 2022).
tumor (continued). "For example, Naa10p interacts with PIX proteins to inhibit Cdc42/Rac1 activity and thus suppress cell motility and tumor metastasis." (PMID 36433943, 2022). "For further analysis, the GlioVis database showed increased mRNA expression levels of CCNB1/CDC42/MAPK7/CD44 oncogenes in GBM tissues compared to non-tumor tissues." (PMID 35008426, 2022). "Actual intensities of active Rac/Cdc42 in normal mucosa and tumor were as follows: 67.29 and 110.92 in all cases, 66.64 and 117.97 in 29 cases (normal mucosa < tumor), 72.01 and 59.83 in 4 cases (normal mucosa > tumor)." (PMID 35110666, 2022). "Here the authors report that TINCR lncRNA encodes pTINCR, a ubiquitin-like protein (UBL) that promotes epithelial differentiation through the SUMOylation and activation of CDC42, and it has tumour suppressor activity in epithelial cancers." (PMID 36369429, 2022). "Overexpression of CDC42 in GBM was demonstrated to promote tumor cell invasion and migration; additionally, CDC42 was associated with low survival rates and drug resistance in GBM patients." (PMID 35008426, 2022). "Cdc42 is involved in the regulation of a variety of tumor and non-tumor diseases through a cascade of multiple signaling pathways." (PMID 35154449, 2022). "Rac/Cdc42 activity seems to be correlated with tumor invasion status evaluated by TNM classification." (PMID 35110666, 2022). "Rac remodels the actin cytoskeleton to accelerate the formation of lamellipodia which drive tumor cell motility, and Cdc42 promotes the formation of actin-rich microspikes to induce direct cell movement." (PMID 36147460, 2022). "In the process of tumor progression, the detection of active Rac/Cdc42 is useful for a better understanding of the migration and invasion abilities of tumor cells and the prediction of metastasis and patient prognosis." (PMID 35110666, 2022). "Of note, in tissue microarray (TMA) samples, 29 of 33 cases demonstrated higher Rac1/Cdc42 activity in the tumor area than the corresponding normal mucosa." (PMID 35110666, 2022). "To address the mechanism underlying pulmonary metastasis, we found that ARHGEF37-mediated Cdc42 activation plays a vital role in lung metastasis via modulation of the adhesion and extravasation of tumor cells." (PMID 35869555, 2022). "In HCC, upregulated CDC42 has been also found in the tumor cell lines, and CDC42 can also promote the expression of PAK1 to advance the malignant behaviors of the tumor cells." (PMID 35340237, 2022). "Steroidogenic acute regulatory protein-related lipid transfer domain-containing protein 13 (StarD13) is a GAP for RhoA and Cdc42 with potential tumor suppressor functions." (PMID 34958986, 2022). "Taken together, we identify a class of therapeutic agents that influence tumor growth by modulating CDC42 signaling in both the tumor cell and its microenvironment." (PMID 35385746, 2022). "In 29 cases, Rac/Cdc42 activity was increased in the tumor region compared to normal mucosa (average Rac/Cdc42 activity, normal mucosa versus tumor = 1: 1.86)." (PMID 35110666, 2022). "RhoGAPs thus inactivate Rho GTPases (Rac1, CDC42) and have generally been presumed to act as tumor suppressors." (PMID 36168627, 2022). "In the present study, we demonstrated that ARHGEF37-mediated Cdc42 activation promoted tumor cell adhesion and further extravasation across the monolayer of the endothelium by enhancing the formation of invadopodia." (PMID 35869555, 2022). "In this study, Rac1, RhoA and CDC42 were all required for tumour cell adhesion to the EC, but only CDC42 was required for the intercalation of tumour cells into the EC." (PMID 34374417, 2021). "Research of Fernando’s group revealed the essential role of CDC42EP3 in matrix remodeling, invasion, angiogenesis and ability to promote tumor growth of CAFs, which was tightly regulated by Cdc42." (PMID 33726765, 2021). "A significant difference in Cdc42 expression was observed between the tumor and normal tissues (χ2 = 3.866, P = 0.049)." (PMID 34221974, 2021).
tumor (continued). "We find that R-ketorolac, a dual Rac1/Cdc42 inhibitor, decreased tumor burden in both a short-term omental engraftment assay and a two-week tumor growth study." (PMID 33413202, 2021). "Oral administration of R-ketorolac for 2 weeks significantly decreased the activity of Rac1 and Cdc42 in tumor lysates when compared to those from placebo control groups." (PMID 33413202, 2021). "By establishing a functional link between CD99 and CDC42 in tumour TEM, we demonstrate that CD99 plays a key role in tumour progression and implicate cell surface CD99 in controlling the diverse activities regulated by CDC42." (PMID 34374417, 2021). "Treatment with R-ketorolac at dosing comparable to that achieved in patients receiving racemic (R−/S-) ketorolac inhibited tumor Rac1 and Cdc42 activity and decreased tumor burden." (PMID 33413202, 2021). "In contrast to the role of CDC42 in inflammation, the well-established effect of CDC42 in tumor promotion paved the way for the description of different targeting strategies." (PMID 33406731, 2021). "Specifically, HGF/Met induces the proliferation and migration of endothelial and tumour cells through RhoA, Rac1, and Cdc42 activation." (PMID 34202487, 2021). "R-ketorolac treatment inhibited tumor Rac1 and Cdc42 activity with little impact on mRNA or protein expression of these GTPase targets." (PMID 33413202, 2021). "Many studies indicated that the expression of these proteins, including RHOA, RHOC, RAC1, RAC2 and CDC42 are upregulated and/or their activities are dysregulated through GEFs, GAPs or GDIs in tumor tissue." (PMID 33406731, 2021). "Together, our results suggest that the reduction in Cdc42 expression in tumor-infiltrating iNKT cells disturbs IL4 polarization and interferes with iNKT cells-DC crosstalk, which contributes to the impaired antitumor Th1 responses mediated by iNKT cells." (PMID 31160756, 2020). "CDC42 gene silencing studies in BC xenografts showed that CDC42 knockdown decreased the tumour cell invasion and metastasis in vivo." (PMID 32445177, 2020). "In this study, we evaluated the expression of TRPV4 in GBM and revealed its role as a tumor promoter, which role is mediated by Cdc42/N-wasp activation and promotion of cellular protrusion formation." (PMID 32843668, 2020). "LAIR-1 strong association with c-MYC and Cdc42, as we observed in our study, and the concomitant high expression of LAIR-1 in these tumours, suggest that these tumours are highly proliferative and are linked with poor prognosis." (PMID 33396670, 2020). "Instead, tumor cells depend on Cdc42 and myotonic dystrophy kinase-related Cdc42-binding protein kinase (MRCK)-mediated regulation of MLC to follow the tracks generated by fibroblasts in the ECM." (PMID 32546182, 2020). "Although other mechanisms may be involved, our study supports the notion that the tumor associated functions of AnxA6 hinge on its ability to modulate the activity of Ca2+ influx channels and to aggregate factors that mediate the activation of small GTPases including Ras, Cdc42 and Rac." (PMID 30719209, 2019). "A central role for the actin cytoskeleton in tumor immune evasion is further supported by an immune escape screen that identified Cdc42 as a mediator of increased resistance to antigen-specific CTL-mediated cytotoxicity." (PMID 31100864, 2019). "Rac1 and Cdc42 are the key members of Rho GTPases, and they can modulate the formation of membrane protrusions during tumor cell migration." (PMID 31057403, 2019). "These non-coding RNAs is extensively involved in Cdc42-induced tumor processes, while many of them are aberrantly expressed." (PMID 30754684, 2019). "It is identified as a tumor suppressor due to its inhibitory regulation of Cdc42 during cell cycle progression." (PMID 30754684, 2019). "In a study of CRC, miR-18a was found to play a tumor suppressor role by inhibiting cell division control protein 42 (CDC42), a mediator of the PI3K pathway." (PMID 31873828, 2019).